TMEM184A (transmembrane protein 184A)
Description:
Acts as a heparin receptor in vascular cells (By similarity). May be involved in vesicle transport in exocrine cells and Sertoli cells (By similarity).
Synonyms: MGC9712; SDMG1; SLC51C1
Tractability: Antibody: UniProt places it where antibodies can reach, with medium confidence; UniProt predicts a signal peptide or a membrane-spanning region; its Gene Ontology location is reachable by antibodies, with medium confidence.
Gene: Protein-coding gene on chromosome 7 (1,542,235 to 1,560,821, reverse strand). Ensembl gene ENSG00000164855.
Subcellular location: Cell membrane; Cytoplasm, perinuclear region; Cytoplasmic vesicle membrane; Early endosome membrane; Endosome; Cytoplasmic vesicle, secretory vesicle membrane
Subcellular location (Human Protein Atlas): Nucleoplasm
Gene Ontology:
Molecular function: heparin binding; transmembrane transporter activity
Biological process: transmembrane transport
Cellular component: cytoplasmic vesicle membrane; early endosome membrane; endosome; perinuclear region of cytoplasm; plasma membrane; secretory granule membrane; membrane; transport vesicle membrane
Genetic constraint (gnomAD): Loss-of-function variants: 40 observed, 38.69 expected, observed/expected ratio (o/e) 1.03, 90% interval 0.8 to 1.35. The upper end of that interval is the gene's LOEUF score, 1.35, which puts it in group 5 of 6, group 1 being the genes least tolerant of losing a copy. Missense variants: 597 observed, 549.49 expected, observed/expected ratio (o/e) 1.09, 90% interval 1.01 to 1.16. Synonymous variants: 275 observed, 245.46 expected, observed/expected ratio (o/e) 1.12, 90% interval 1.01 to 1.24.
Homologues: Orthologues: chimpanzee TMEM184A (99% identical), macaque TMEM184A (96% identical), guinea pig TMEM184A (85% identical), rat Tmem184a (84% identical), mouse Tmem184a (83% identical), pig TMEM184A (83% identical), dog TMEM184A (74% identical), tropical clawed frog tmem184a (71% identical), zebrafish tmem184a (65% identical), Caenorhabditis elegans tmem-184 (51% identical). Paralogues in human: TMEM184B (61% identical), TMEM184C (31% identical), SLC51A (13% identical).
Diseases named in the same sentence as TMEM184A in open-access papers:
TMEM184A is named in the same sentence as 7 diseases in open-access papers, as found by Europe PMC text mining. Sharing a sentence is not in itself a finding about the gene and the disease. The quoted sentences say what the papers report.
gastric cancer (2 papers, 2015 to 2024). A primary or metastatic malignant neoplasm involving the stomach. "In addition, we discovered some novel genes, such as TMEM184A, PSAPL1, KIAA1199, CLRN3 and FNDC1, which have not been reported in gastric cancer previously, and their roles in cancer remain unknown." (PMID 25928635, 2015).
atherosclerosis (1 paper, 2025). A disease characterized by the build-up of fatty material and calcium deposition in the arterial wall resulting in partial or complete occlusion of the arterial lumen. "Elucidating TMEM184A’s role specific to the regulation of permeability, cell proliferation, and migration in vascular cells will provide us with new knowledge required to develop therapeutic strategies that target TMEM184A to slow the progression of chronic inflammation in atherosclerosis." (PMID 40498012, 2025).
glioma (1 paper, 2024). A benign or malignant brain and spinal cord tumor that arises from glial cells (astrocytes, oligodendrocytes, ependymal cells). "At the protein level, based on the reported effect of TMEM184A on PDGFR signaling, and the known importance of this growth factor receptor in glioma proliferation, we assessed the expression of PDGFR-beta." (PMID 39594630, 2024).
SARS-CoV infection (1 paper, 2020). "Another downregulated gene in the SARS-CoV infection was transmembrane protein 184A (TMEM184A), which was necessary for heparin responses in endothelial cells and vascular smooth muscle cells with interruption effect on the anti-inflammatory responses of endothelial cells to heparin." (PMID 32754004, 2020).
cancer (4 papers, 2015 to 2026). A tumor composed of atypical neoplastic, often pleomorphic cells that invade other tissues. "For the TMEM184A gene, there are few reports on its pathophysiology in inflammation and cancer progression." (PMID 33670198, 2021).
TMEM184A also shares sentences with these, for which no sentence is quoted: ovarian endometriosis (2 papers); tumours (1).